SNORD65 (small nucleolar RNA, C/D box 65)
Synonyms: HBII-135; SNORD65A
Gene: Small nucleolar RNA gene on chromosome 17 (16,441,226 to 16,441,298, forward strand). Ensembl gene ENSG00000277512.
Gene Ontology:
Biological process: RNA processing
Cellular component: nucleolus
Homologues: Orthologues: macaque SNORD65 (99% identical), mouse Snord65 (95% identical), pig SNORD65 (93% identical), rat Snord65 (92% identical), rabbit SNORD65 (90% identical). Paralogues in human: SNORD65B (89% identical), SNORD65C (89% identical).